TUBA4A (tubulin alpha 4a)
Description:
Tubulin is the major constituent of microtubules, a cylinder consisting of laterally associated linear protofilaments composed of alpha- and beta-tubulin heterodimers. Microtubules grow by the addition of GTP-tubulin dimers to the microtubule end, where a stabilizing cap forms. Below the cap, tubulin dimers are in GDP-bound state, owing to GTPase activity of alpha-tubulin.
Synonyms: TUBA1; FLJ30169; H2-ALPHA; ALS22; CMYO26; FTDALS9; OZEMA23; SPAX11
Tractability: Small molecule: an approved drug acts on it; a high-quality ligand is known; it belongs to a druggable protein family. Antibody: its Gene Ontology location is reachable by antibodies, with high confidence. PROTAC: ubiquitination databases record sites on it; its protein half-life has been measured; a small molecule that binds it is known. Other modalities: an approved drug acts on it.
Target class: Structural protein
Gene: Protein-coding gene on chromosome 2 (219,249,710 to 219,277,902, reverse strand). Ensembl gene ENSG00000127824.
Subcellular location: Cytoplasm, cytoskeleton
Subcellular location (Human Protein Atlas): Microtubules; Primary cilium
Pathways (Reactome):
Cell Cycle: AURKA Activation by TPX2; EML4 and NUDC in mitotic spindle formation; Loss of Nlp from mitotic centrosomes; Loss of proteins required for interphase microtubule organization from the centrosome; Mitotic Prometaphase; Recruitment of NuMA to mitotic centrosomes; Recruitment of mitotic centrosome proteins and complexes; Regulation of PLK1 Activity at G2/M Transition; Resolution of Sister Chromatid Cohesion; Sealing of the nuclear envelope (NE) by ESCRT-III; Separation of Sister Chromatids; The role of GTSE1 in G2/M progression after G2 checkpoint
Vesicle-mediated transport: COPI-dependent Golgi-to-ER retrograde traffic; COPI-independent Golgi-to-ER retrograde traffic; COPI-mediated anterograde transport; Gap junction assembly; Microtubule-dependent trafficking of connexons from Golgi to the plasma membrane; Translocation of SLC2A4 (GLUT4) to the plasma membrane
Metabolism of proteins: Carboxyterminal post-translational modifications of tubulin; Formation of tubulin folding intermediates by CCT/TriC; Post-chaperonin tubulin folding pathway; Prefoldin mediated transfer of substrate to CCT/TriC
Organelle biogenesis and maintenance: Anchoring of the basal body to the plasma membrane; Cargo trafficking to the periciliary membrane; Intraflagellar transport
Signal Transduction: Hedgehog 'off' state; RHO GTPases Activate Formins; RHO GTPases activate IQGAPs
Hemostasis: Kinesins; Platelet degranulation
Immune System: MHC class II antigen presentation; PKR-mediated signaling
Neuronal System: Activation of AMPK downstream of NMDARs; Assembly and cell surface presentation of NMDA receptors
Autophagy: Aggrephagy
Cellular responses to stimuli: HSP90 chaperone cycle for steroid hormone receptors (SHR) in the presence of ligand
Developmental Biology: Recycling pathway of L1
Disease: HCMV Early Events
Gene Ontology:
Molecular function: protein binding; protein kinase binding; GTP binding; GTPase activity; structural constituent of cytoskeleton; enzyme binding
Biological process: mitotic cell cycle; neuron differentiation; cytoskeleton organization; microtubule-based process
Cellular component: cilium; cytoskeleton; extracellular exosome; microtubule; microtubule cytoskeleton; cytosol; extracellular region
Genetic constraint (gnomAD): Loss-of-function variants: 23 observed, 34.47 expected, observed/expected ratio (o/e) 0.67, 90% interval 0.48 to 0.94. The upper end of that interval is the gene's LOEUF score, 0.94, which puts it in group 4 of 6, group 1 being the genes least tolerant of losing a copy. Missense variants: 279 observed, 620.02 expected, observed/expected ratio (o/e) 0.45, 90% interval 0.41 to 0.5. Synonymous variants: 216 observed, 240.64 expected, observed/expected ratio (o/e) 0.9, 90% interval 0.8 to 1.
Gene-disease validity (ClinGen):
ClinGen rates the evidence that TUBA4A causes each of these diseases.
amyotrophic lateral sclerosis type 22 (autosomal dominant): Moderate. Any amyotrophic lateral sclerosis in which the cause of the disease is a mutation in the TUBA4A gene.
autosomal dominant macrothrombocytopenia (autosomal dominant): Limited. This syndrome is characterized by congenital thrombocytopenia associated with the presence of large platelets.
Homologues: Orthologues: chimpanzee TUBA4A (100% identical), dog TUBA4A (100% identical), guinea pig TUBA4A (100% identical), mouse Tuba4a (100% identical), rabbit TUBA4A (100% identical), rat Tuba4a (100% identical), macaque TUBA4A (99% identical), pig TUBA4A (99% identical), tropical clawed frog tuba4b (98% identical), zebrafish tuba8l2 (95% identical). Paralogues in human: TUBA1B (97% identical), TUBA1A (96% identical), TUBA1C (96% identical), TUBA3C (95% identical), TUBA3D (95% identical), TUBA3E (93% identical), TUBA8 (90% identical), TUBAL3 (73% identical), TUBB (43% identical), TUBB3 (43% identical), TUBB4B (43% identical), TUBB4A (42% identical), and 11 more.
Diseases named in the same sentence as TUBA4A in open-access papers:
TUBA4A is named in the same sentence as 65 diseases in open-access papers, as found by Europe PMC text mining. Sharing a sentence is not in itself a finding about the gene and the disease. The quoted sentences say what the papers report.
amyotrophic lateral sclerosis (12 papers, 2020 to 2025). Amyotrophic lateral sclerosis (ALS) is a neurodegenerative disease characterized by progressive muscular paralysis reflecting degeneration of motor neurons in the primary motor cortex, corticospinal tracts, brainstem and spinal cord. "TUBA4A mutations have been linked to neurodegenerative diseases such as amyotrophic lateral sclerosis (ALS) and frontotemporal dementia (FTD)." (PMID 35669725, 2022). "Recently, disease-associated variants of the TUBA4A gene were identified in patients with amyotrophic lateral sclerosis (ALS) and frontotemporal dementia (FTD)." (PMID 35327632, 2022). "Interestingly, a similar pathogenic mechanism has been proposed for the p.W407X substitution in TUBA4A, which has been associated to a severe phenotype of amyotrophic lateral sclerosis." (PMID 37435044, 2023). "It is plausible that mutations in TUBA4A are enriched in amyotrophic lateral sclerosis due to the heightened requirements for axonal transport in motor neurons and a specific role for α tubulin 4A in these cells, however this is yet to be addressed experimentally in any depth." (PMID 34897416, 2021). "As delineated in preceding sections, both NEFH and TUBA4A demonstrate robust associations with amyotrophic lateral sclerosis (ALS)." (PMID 41394403, 2025). "Twelve non-synonymous variants in TUBA4A and four changes leading to premature truncation were identified in about 1% of familial amyotrophic lateral sclerosis (ALS), and 0.4% of sporadic ALS patients." (PMID 37418012, 2023). "This expression pattern may explain why, differently from congenital tubulin mutations, mutations in TUBA4A cause amyotrophic lateral sclerosis (ALS), a late-onset disease characterized by adult-onset upper and lower motor neuron degeneration." (PMID 33027950, 2020). "Separate missense or loss-of-function variants in TUBA4A have been reported in amyotrophic lateral sclerosis (MIM616208) but not with oCCDDs." (PMID 38585811, 2024).
frontotemporal dementia (8 papers, 2019 to 2025). Frontotemporal dementia (FTD) comprises a group of neurodegenerative disorders, characterized by progressive changes in behavior, executive dysfunction and language impairment, as a result of degeneration of the medial prefrontal and frontoinsular cortices. "A novel N-terminal TUBA4A frameshift mutation was recently discovered in an individual with a family history of Parkinsonism and exhibiting frontotemporal lobar degeneration." (PMID 37150812, 2023). "Alpha4a-tubulin (TUBA4A) mutations are strongly linked to familial ALS and frontotemporal dementia." (PMID 37150812, 2023). "Although ALS is the predominant phenotype in TUBA4A mutation carriers, a few cases were diagnosed with cognitive problems or frontotemporal dementia (FTD) with or without ALS, and one case showed nigropathy with parkinsonism without ALS." (PMID 37418012, 2023).
tubulinopathies (5 papers, 2023 to 2025). "Mutations in tuba1a, tubb2a, and tuba4a have all been linked to a group of clinical neurodevelopmental disorders known as tubulinopathies." (PMID 39453165, 2024). "To examine the applicability of GFP11-i labeling across multiple species, we tested this technique with the human α-tubulin isotype hTUBA1A, β-tubulin hTUBB8, and mouse α-tubulin TUBA4A, all of which had been implicated in tubulinopathies." (PMID 39159282, 2024). "In fact, primary neurodegenerative tubulinopathies, caused mainly by mutations in genes encoding the components of the tubulin cytoskeleton, especially in TUBA4A, TUBB2A, and TUBB3 genes, have been excellently reviewed and comprehensively discussed recently." (PMID 36352320, 2023). "These can be either primary neurodegenerative tubulinopathies (caused by mutations in genes coding for components of microtubules, like TUBA4A, TUBB2A, and TUBB3) or disorders caused by various pathogenic interactions and transactions between different compounds and tubulin cytoskeleton." (PMID 36352320, 2023).
E. coli infection (4 papers, 2015 to 2020). "In line with this concept, KEGG enrichment revealed HCLS1 and TUBA4A to be enriched for Pathogenic Escherichia coli infection (hsa05130; 2/53) and Tight junction (hsa04530; 2/167)." (PMID 32371984, 2020). "Analysis on the basis of the KEGG revealed HCLS1 and TUBA4A to be enriched for Pathogenic Escherichia coli infection (hsa05130; 2/53) and Tight junction (hsa04530; 2/167)." (PMID 32371984, 2020). "Enrichment analysis using the KEGG database revealed the significant participation of detected proteins in pathogenic E. coli infection (ACTG1, TUBA1C, TUBA4A, TUBB, TUBB8, and YWHAZ), which may indicate microbiota changes associated with being in space." (PMID 31547269, 2019). "However RRMS clinic subtype patients also show an increase in the ACTB, KRT18, FYN, TUBA4A, NCL, CTNNB1 proteins which are a part of pathogenic E. coli infection pathway, which induce the mobilization of inflammatory cells." (PMID 25942430, 2015).
breast carcinoma (3 papers, 2020 to 2025). "Although little is known about roles of ARNTL2 and TUBA4A in LUAD, ARNTL2 was reported to be associated with tumor progressions and metastases in colorectal and breast cancers." (PMID 32592319, 2020). "Despite this discrepancy, SEH1L, similar to ZYX, GJA1, and TUBA4A, was upregulated in DOX-resistant breast cancer cells in the independent transcriptomic dataset GSE76540." (PMID 41153808, 2025).
Infertility (3 papers, 2023 to 2024). "Recently, several missense mutations in TUBA4A were identified to cause oocyte developmental arrest and human infertility." (PMID 39159282, 2024). "In summary, our results suggest that human sperm with de novo TUBA4A mutations, if successfully fertilized in the egg, will lead to infertility of the female offspring." (PMID 39872894, 2023). "The TUBA4A (E284G) de novo mutation was implicated in human infertility, and this pathogenic mutation could led to meiotic arrest in mouse oocytes in a dominant-negative manner." (PMID 39159282, 2024). "We further performed functional assays on the effects of DNMs in Tubulin Alpha 4a (TUBA4A), which showed the most significant enrichment of rare DNMs in our infertile parent–child trios." (PMID 37024973, 2023). "Among the genes, TUBA4A was the most significantly enriched in our infertile parent–child trios." (PMID 37024973, 2023). "We found 4 genes (TUBA4A, UBQLN1, HTR2C, and ZFPM2) with at least two damaging DNMs in infertile females and these 4 genes were significantly enriched in our affected individuals compared to other control groups." (PMID 37024973, 2023). "We perform functional assays on the effects of DNMs in a representative gene Tubulin Alpha 4a (TUBA4A), which shows the most significant enrichment of DNMs in the infertile parent–child trios." (PMID 37024973, 2023).
lung carcinoma (3 papers, 2019 to 2024). "As TUBA4A is a component of microtubules, the effectiveness of microtubule-targeting drugs (e.g., paclitaxel-like drugs) may be impacted in lung cancer treatment." (PMID 38200058, 2024). "The abundance of TLN1, TUBA4A, HSPA8, ITGB3, TSG101, and PACSIN2 in the plasma of lung cancer patients was measured using targeted mass spectrometry and compared to that in plasma from healthy volunteers." (PMID 34684727, 2021). "Together, these observations suggest that FN1, TLN1, ITGB3, HSPA8, and TUBA4A detection in the blood using SRM/SIS may serve as an indicator of tumors, and elevations in their concentrations coupled with PACSIN2 detection discriminate lung cancer from other malignancies." (PMID 34684727, 2021).
motor neuron disease (3 papers, 2023 to 2025). "The clinical picture is different from previous phenotypes associated with TUBA4A mutations that encompass motor neuron disease with signs of first and second motor neurons (ALS-like), FTD or non-specific dementia with or without ALS, and parkinsonism without ALS in one case." (PMID 37418012, 2023).
Parkinsonism (3 papers, 2022 to 2025). Characteristic neurologic anomaly resulting from degeneration of dopamine-generating cells in the substantia nigra, a region of the midbrain, characterized clinically by shaking, rigidity, slowness of movement and difficulty with walking and gait. "Here, we present the neuropathological report of a patient with the semantic variant of primary progressive aphasia with a family history of Parkinsonism, harboring a novel frameshift mutation c.187del (p.Arg64Glyfs*90) in TUBA4A." (PMID 35327632, 2022). "Noteworthy, TH, dopamine receptor 2 (DRD2), SLC6A3/DAT, SLC18A2, tubulin beta 2A (TUBB2A), tubulin alpha 4A (TUBA4A), and tubulin beta 3 (TUBB3) were the 7 key genes enriched in the Parkinson disease pathway." (PMID 40259945, 2025).
cardiomyopathy (2 papers, 2022 to 2025). A disease of the heart muscle or myocardium proper. "Elevated TUBA4A in human cardiomyopathy contributes to the increased detyrosination that impedes myocyte function." (PMID 35433678, 2022).
glioma (2 papers, 2021 to 2022). A benign or malignant brain and spinal cord tumor that arises from glial cells (astrocytes, oligodendrocytes, ependymal cells). "Among the 10 candidates, high mRNA expression of CCL8, FCGR2B, and TUBA4A and low mRNA expression of GABRD, PRAME, and SYN1 were significantly correlated with worse prognosis, while the mRNA expression of CCL18, SCN1B, SNCB, and VSNL1 showed no connection to the overall survival of glioma patients." (PMID 36685974, 2022).
schizophrenia (2 papers, 2023 to 2024). A major psychotic disorder characterized by abnormalities in the perception or expression of reality. "Expression of the ‘Macroautophagy’ genes AMBRA1, PRKAB1, TUBA1A, TUBB2A, and TUBA4A was restored in the AT-schizophrenia group." (PMID 38648100, 2024).
spastic ataxia (2 papers, 2023 to 2026). "Our findings widen the phenotypic and genetic manifestations of TUBA4A variants and add a new type of spastic ataxia to be taken into consideration in the differential diagnosis." (PMID 37418012, 2023).
acne (1 paper, 2021). An inflammatory process of the sebaceous glands which is characterized by comedones, nodules, papules and/or pustules on the skin. "Msn is regulated by tight junction assembly in the tight junction barrier, while Tuba4a was found to be significantly up-regulated in acne rat." (PMID 34539397, 2021).
Alzheimer ́s disease (1 paper, 2022). "In a further approach, we crossbred wild-type (+/+) or Tuba4a mutant mice (p/p) with a tauopathy mouse model (hTau), known for its Alzheimer ́s disease-like pathology, as characterized by the pathologic oligomerization of hyper-phosphorylated Tau in cell bodies and dendrites." (PMID 35858909, 2022). "The inability of Tau to efficiently bind and colocalize with non-polyglutamylated Tuba4a prompted us to analyze the Tau phosphorylation status, since Tau hyper-phosphorylation and microtubule-detachment are hallmarks in Alzheimer ́s disease (AD) and other tauopathies." (PMID 35858909, 2022).
Ataxia (1 paper, 2025). Ataxia refers to impaired coordination of voluntary muscle movement. "In the remaining two families, we observed probands with cerebellar ataxia and epilepsy accompanying proximal and axial muscle weakness, establishing the first documented association between TUBA4A variants and multisystem proteinopathy." (PMID 40666348, 2025).
breast tumors (1 paper, 2022). "Significantly overexpressed in migratory BC cells and identified as a highly expressed gene in primary breast tumors with brain-specific metastasis, TUBA4A was found as overexpressed in MCF7 BC cell line in upregulated JTB condition of this experiment." (PMID 36500393, 2022).
colorectal cancer (1 paper, 2019). A primary or metastatic malignant neoplasm that affects the colon or rectum.
COVID-19 (1 paper, 2023). A disease caused by infection with severe acute respiratory syndrome coronavirus 2. "The remaining 8 key genes (EGR2, HIST1H3H, HIST1H4H, HIST1H4I, HIST1H4K, MTHFD2, TUBA4A, and TUBB1) were less studied in the roles of COVID-19 and OA, emphasizing their importance in future research." (PMID 37291167, 2023).
female infertility (1 paper, 2023). Diminished or absent ability of a female to achieve conception. "To further confirm the genetic contribution of TUBA4A in female infertility with oocyte and embryo defects, we performed gene burden test among 1155 sporadic female infertility cases and 2813 internal controls." (PMID 37024973, 2023). "Based on previous published studies, we speculated that other three genes (UBQLN1, HTR2C, and ZFPM2) may also play a role in female infertility besides TUBA4A." (PMID 37024973, 2023). "In this study, all affected individuals with TUBA4A mutations only exhibited the phenotype of female infertility without any abnormalities in somatic tissues or organs." (PMID 37024973, 2023).
Macrothrombocytopenia (1 paper, 2019). "Indeed, mice carrying a missense mutation in the Tuba4a gene, and a patient with a monoallelic double missense mutation in the TUBA4A gene displayed macrothrombocytopenia and structural abnormalities in the marginal band of platelets." (PMID 30760556, 2019).
neuroblastoma (1 paper, 2023). Neuroblastoma (NB) is the most common solid, extracranial childhood tumor. "Conversely, a transcriptomic study on neuroblastoma SK-N-SH cells revealed that SARS-CoV-2 infection induced a downregulation of several members of building blocks of the cytoskeleton, as well as some of their regulators (i.e., TUBA1A, TUBA4A, TUBB4A, STMN4, TMSB15A, SYNPO2)." (PMID 37896797, 2023).
proteinopathy (1 paper, 2025). "Variable accumulation of phosphorylated TDP-43, often considered a marker of a proteinopathy, showed that different TUBA4A variants might result in distinct level of protein accumulations." (PMID 40666348, 2025). "In our study, we present a gamut of TUBA4A-related primary myopathies and multisystem proteinopathies, providing detailed clinical and functional insights." (PMID 40666348, 2025). "Immunohistochemical staining showed evidence of proteinopathy, with autophagic features and TUBA4A accumulation in patient myofibres." (PMID 40666348, 2025).